TLE1 (TLE family member 1, transcriptional corepressor)
Diseases named in the same sentence as TLE1 in open-access papers (continued):
Sharing a sentence is not in itself a finding about the gene and the disease.
cancer (28 papers, 2010 to 2025). A tumor composed of atypical neoplastic, often pleomorphic cells that invade other tissues. "It is therefore important to elucidate the mechanisms underlying TLE1 function during cancer initiation and metastasis." (PMID 27852056, 2017). "It was also found that, within a human lung tumor tissue array, a significant number of carcinomas overexpress TLE1 and correlate with malignancy in cancer, regarded as a biomarker to predict the prognosis of LUAD patients." (PMID 35281055, 2022). "TLE1 negatively regulates apoptosis and can protect caspase-independent malignant cancer cells from Bit1-induced cell death." (PMID 27852056, 2017). "TLE1 negatively regulates inflammation and has potential roles in various diseases, including cancer." (PMID 27852056, 2017). "TLE1 is a major counter-regulator of inflammation and has potential functions in a variety of inflammatory diseases in addition to cancer." (PMID 27852056, 2017). "In this review, we highlight the functions of TLE1 in cancer and explore targeted approaches for cancer diagnosis and treatment." (PMID 27852056, 2017). "Transducin-like enhancer of split 1 (TLE1), a human orthologue of the Drosophila developmental corepressor Groucho (Gro), acts as an anti-proliferative factor, and TLE family members have been linked to human cancers." (PMID 37260146, 2023). "However, in cancer cells, overexpression of TLE1 can suppress anoikis by competing with TLE5 for Bit binding and sequestering TLE5 in the nucleus." (PMID 36438567, 2022). "The prognostic value of TLE1 expression was evaluated in other types of cancer." (PMID 34048198, 2021). "In the following sections, we highlight the functions of TLE1 in various cancers." (PMID 27852056, 2017). "In light of its anti-differentiation and growth promoting function in cellular systems, it is not surprising that TLE1 has been implicated in the pathogenesis of cancer." (PMID 29069783, 2017). "The functions of TLE1 differ in breast compared to other cancers." (PMID 27852056, 2017). "Unfortunately, the mechanism of TLE1 action in this cancer remains unknown." (PMID 27852056, 2017). "Indeed, the data suggest that TLE1 is widely expressed in all types of cancer." (PMID 27852056, 2017). "Defining signatures in chromatin facilitators involved in cancer characterized some of the pioneer factors like the GATA family of proteins, TLE1 protein, and PBX1 as a valuable prognostic biomarker in BC." (PMID 36046086, 2021). "TLE1 was used in 14 other cases and found to be focally positive in other tumors including MPNST, carcinoma, and SFT." (PMID 33061792, 2020). "We also identified the top 1 GEAR in individual cancer types, such as TLL1 (BLCA), PGK1 (BRCA), RFXANK (CESC), DPP7 (COAD), VWA8 (KIRC), SCMH1 (LGG), HILPDA (LIHC), TLE1 (LUAD), CD151 (LUSC), ANKRD13A (OV), SOCS2 (PAAD), DRG2 (PRAD), ADAMTS6 (STAD), PSMB8 (THCA), ASS1 (UCEC)." (PMID 41404730, 2025). "TLE5 overexpression inhibited Notch signaling activation through recruitment of TLE1 and HDAC3, converting active Notch transcriptional complexes into repressive complexes, which reduced the expression of Notch target genes such as HES1 in clone cancer cells." (PMID 36438567, 2022). "Through the study it was concluded that the highly prospected pioneer TFs in BC, including FOXA1, TLE1, PBX1, and GATA3, possess the potential therapeutic significance and further innovations in the field could yield targeted therapy in cancer treatment." (PMID 36046086, 2021).
infection (2 papers, 2022 to 2023). The state of being infected such as from the introduction of a foreign agent such as serum, vaccine, antigenic substance or organism. "Several variants (rs17763742 near LZTFL1, rs2834164 in IFNAR2 and rs1826292621 near TLE1) showed a significant difference in effect sizes (SNP*sex interaction P < 0.0031, adjusted probability for 16 comparisons) linked not only to hospitalization, but also to critical illness and infection risk." (PMID 35708486, 2022). "We also found 12 genes associated with infection at six loci, including four infection-specific genes (TCF19, ABO, OBP2B, and TLE1)." (PMID 37886583, 2023).
TLE1 also shares sentences with these, for which no sentence is quoted: Alzheimer disease (4 papers); solitary fibrous tumor (4); epithelioid sarcoma (2); leukemia (2); metabolic disorders (2); metastatic disease (2); neuroblastoma (2); neurofibroma (2); rhabdomyosarcoma (2); sarcomatoid carcinoma (2); soft tissue sarcoma (2); spindle cell rhabdomyosarcoma (2); triple-negative breast carcinoma (2); acinar adenocarcinoma (1); adenocarcinoma (1); adenoma (1); alcohol (1); alcoholic liver damage (1); angiosarcoma (1); basal cell adenocarcinomas (1); biphasic mesothelioma (1); cardiovascular diseases (1); Cerebral ischemia (1); Cognitive impairment (1); colorectal cancer (1); depression (1); dermatitis psoriasiform (1); dermatofibrosarcoma protuberans (1); diabetic retinopathy (1); digestive system neoplasm (1).
A further 30 diseases each share a sentence with TLE1 in 1 paper.